ENO1 (enolase 1)
Diseases named in the same sentence as ENO1 in open-access papers (continued):
Sharing a sentence is not in itself a finding about the gene and the disease.
cancer (continued). "Here, we show that ENO1 is widely expressed in normal human tissues and is significantly upregulated in most TCGA (The Cancer Genome Atlas) cancer patients." (PMID 36845730, 2023). "The multifunctional glycolytic enzyme ENO1 has been shown to be commonly over-expressed in various human cancers including PC." (PMID 36845730, 2023). "ENO1 is expressed on the cell surface, can promote cancer invasion, and is subject to a series of specific post-translational modifications, such as acetylation, methylation, and phosphorylation." (PMID 37959729, 2023). "ENO-1 acts as a glycolytic enzyme and promotes invasion and metastasis formation in various cancers." (PMID 36841765, 2023). "The differential expression of Eno1 leads to several diseases, including cancer, Alzheimer's disease and rheumatoid arthritis." (PMID 37125075, 2023). "A previous study identified a potent inhibitor of ENO1, macrosphelide A, which demonstrates anti-cancer effects by simultaneously inactivating ENO1, aldolase, and fumarase." (PMID 36768924, 2023). "Meanwhile, GSEA revealed that genes encoding for mitochondrial functions and lipid metabolism were significantly upregulated in ENO1 knockout cells, indicating a shift in metabolism patterns in cancer cells." (PMID 36845730, 2023). "Our data are in line with previous published reports implicating ENO1 in various aspects of human cancers." (PMID 37190091, 2023). "The presence of autoantibodies against ENO-1 correlated with a better prognosis in PDA, suggesting that ENO-1 was a good molecular candidate for improving immune cell response to cancers." (PMID 36768924, 2023). "In this study, ENO1 was abundantly expressed in cancer tissues and was correlated with poor prognosis." (PMID 37810778, 2023). "It is worth noting that ENO1 has been identified to be overexpressed in over 70 percent of global cancers, covering highly metastatic HCC cells, and predicted a worse prognosis of HCC." (PMID 38069309, 2023). "There is also evidence that other modifications including O‐GlcNAcylation, acetylation, and methylation regulate the function of ENO1, and the level of these modifications in cancer cells is significantly higher than that in normal cells." (PMID 36999124, 2023). "A pan-cancer analysis showed that ENO-1 expression correlated with immune cell infiltration, including B cells, CD8+ and CD4+ T-cells, macrophages, neutrophils, and dendritic cells." (PMID 36768924, 2023). "Studies have demonstrated that ENO1 promotes the migration and metastasis of cancer cells via the mechanism of regulating intravascular and pericyte fibrinolytic activity." (PMID 37671155, 2023). "ENO1 also plays a role in tumorigenesis and cancer progression in various cancer types, including HCC." (PMID 37508544, 2023). "Eno1, a glycolytic enzyme, is frequently upregulated in cancer cells and increases the Warburg effect." (PMID 37125075, 2023). "Inhibition of ENO1 alone or in combination with other pathways activated by ENO1 knockout, opens novel avenues for future cancer therapeutic approaches." (PMID 36845730, 2023). "The overexpression of ENO-1 in cancer cells can also contribute to cisplatin resistance in different cancer types and is considered a biomarker to predict prognosis and drug resistance in cancers." (PMID 36768924, 2023). "At the same time, ENO1 has been shown to regulate many signaling pathways involved in cancer development, including PI3K/AKT, AMPK/mTOR, and WNT/β-catenin." (PMID 36768425, 2023). "While the concentration of ENO1 is important in these cancer types, little is known about the role of ENO1 in SKCM." (PMID 35925486, 2022). "ENO1 has been reported to sustain proliferation and inhibit apoptosis in multiple types of malignant tumors." (PMID 36476328, 2022). "In the GC cases, differential ENO1 expressions were detected between the cancer tissues and the paracancerous tissues." (PMID 36295613, 2022).
cancer (continued). "When the shortlisted, upregulated proteins in GC were investigated by network enrichment analysis, as expected, many proteins from metabolic pathways were detected, including α-enolase (ENO1), previously earmarked as a cancer biomarker." (PMID 35566209, 2022). "ENO1 is the major isoform of enolase in cancer cells, accounting for 75–90% of the cellular enolase activity." (PMID 35954207, 2022). "There is an increasing number of studies reporting the overexpression of ENO1 in human cancers, making it a candidate for a promising therapeutic and diagnostic target in various types of cancers." (PMID 35204345, 2022). "ENO1 is multifunctional, participating in biological growth, development, and reproduction; parasitic infections; cancer occurrence and metastasis; autoantigen activity; bacterial and fungal infections; and cell stress." (PMID 35925486, 2022). "The findings indicate that not only is the ENO1 expression level related to the co-culture duration, but also that it differs between the cancer cell and the normal cell in ENO1 response to H. pylori infection." (PMID 36295613, 2022). "At the same time, the silencing of ENO1 substantially elevated the rate of cancer cell apoptosis by inducing the upregulation of apoptosis-related protein Bax and the downregulation of Bcl-2." (PMID 35434271, 2022). "Accumulated evidence demonstrates that, in the majority of cancers, ENO1 overexpression contributes to cancerous cell survival, proliferation, and the maintenance of the Warburg effect." (PMID 35204345, 2022). "More importantly, the methylated form, ENO1R50me, is found to affect cancer cell motility since the replacement of ENO1R50 by lysine diminished ENO1-triggered cell invasion." (PMID 35434271, 2022). "ENO1 has a crucial role in maintaining the Warburg effect, thus supporting cancer cell proliferation and formation of metastases." (PMID 35204345, 2022). "As a glycolytic enzyme, ENO1 contributes to the Warburg effect and provides ATP to promote cancer development and progression." (PMID 35844805, 2022). "A chimeric anti-ENO1 monoclonal antibody (ChenO1-22) can attenuate cancer cell invasion by inhibiting ENO1-mediated GSK3β inactivation to promote SLUG protein ubiquitination and block metastasis." (PMID 36620599, 2022). "Numerous studies have found that ENO1 can promote proliferation and inhibit apoptosis in various types of malignant tumors cells." (PMID 35434271, 2022). "Taking into consideration the correlation between ENO1 overexpression and worse cancer prognosis, ENO1 stands out as a discriminatory cancer biomarker." (PMID 35434271, 2022). "Although ENO1 traditionally is considered a glycolytic enzyme, it has other functions including a role in the metastatic potential of cancer." (PMID 35042842, 2022). "This review summarizes the relationship between ENO1 and hallmarks of cancer, elucidates the regulators and post-translational modifications of ENO1, as well as explaining the therapeutic applications of ENO1." (PMID 35434271, 2022). "This review summarizes the up-to-date knowledge about the relationship between ENO1 and cancer, examines ENO1's potential as a cancer biomarker, and discusses ENO1's role in novel onco-immunotherapeutic strategies." (PMID 35434271, 2022). "More importantly, the consistent correlation between overexpression of ENO1 on multiple cancer types and worse clinical outcomes suggests its key role in activating oncogenic signaling pathways and positions it to be an optimal therapeutic target." (PMID 35434271, 2022). "Multiple studies have shown that overexpression of ENO1 positively correlates to invasion, migration, and metastasis in various types of cancers." (PMID 35434271, 2022). "In summary, ENO1 is expected to be a useful cancer biomarker for guiding patient management and changing disease timelines." (PMID 35434271, 2022).
cancer (continued). "An increase in ENO1 expression has been reported in human diseases (i.e., systemic sclerosis, type II diabetes mellitus, lupus, Alzheimer disease) and many cancers, as well as being involved in cell growth and hypoxia tolerance." (PMID 36139550, 2022). "It is well-recognized that ENO1 plays a key role in the Warburg effect and promotes proliferation, migration, and invasion of cancer cells by accelerating glycolysis." (PMID 36481875, 2022). "Conversely, siRNA-mediated knockdown of ENO1 counteracted the effects of lncRNA P5848 on cancer cell growth, cell survival, and migration." (PMID 35434271, 2022). "Ultimately, the pre-clinical success of using combinatorial therapy of novel ENO1-targeting inhibitors along with traditional chemotherapy sheds light of hope to patients who have borne “cureless” cancers." (PMID 35434271, 2022). "ENO1 has been found to promote tumorigenesis, proliferation, and migration in many types of cancers." (PMID 36620599, 2022). "Increased levels of antibodies against phospho-ENO1 correlate with survival rate in cancer patients." (PMID 36077431, 2022). "Several glucose transporters and glycolytic enzymes in cancer cells are involved in the Warburg effect, which is capable of activating and overexpressing ENO1." (PMID 35805203, 2022). "We used the Sangerbox platform to analyze data from TCGA and GTEx to evaluate the expression level of ENO1 in different human cancers." (PMID 35925486, 2022). "Alpha-enolase (ENO1) is a glycolytic metalloenzyme, and its overexpression occurs in numerous cancers, contributing to cancer cell survival, proliferation, and maintenance of the Warburg effect." (PMID 35204345, 2022). "On the surface of cancer cells, ENO1 acts as a plasminogen receptor, promoting the degradation of plasminogen to plasmin, a serine protease involved in the degradation of extracellular matrix, thus facilitating the invasion and metastasis of the cell." (PMID 35251177, 2022). "Among the four subtypes of enolase, ENO1 is ubiquitously expressed in most human tissues and overexpressed in a myriad of cancer types." (PMID 35434271, 2022). "Of particular note, few studies have also elevated the circulating level of ENO1 in cancer patients." (PMID 35836227, 2022). "lncRNA P5848 can upregulate both gene and protein expression levels of ENO1, promoting cancer cell growth." (PMID 35434271, 2022). "Overexpression of ENO1 was related to lymph node metastasis of multifarious malignant neoplasms, such as breast cancer and pancreatic cancer." (PMID 36361568, 2022). "ENO1, in addition to deregulating the bioenergetics of cancer cells, was reported to sustain cell proliferation, to induce resistance to death, and to promote invasion and metastasis, in addition to angiogenesis." (PMID 36139435, 2022). "ENO1 can affect the physiological metabolism in cancer cells and is expected to be a novel pharmacological target for cancer treatment." (PMID 35434271, 2022). "Hypoxic cancers exhibit elevated glycolysis and glycolytic enzymes, including ENO1, which is involved in the Warburg effect." (PMID 36476328, 2022). "For example, hexokinase, fructose 1,6-diphosphate phosphofructokinase, kinase muscle isomer 2, and pyruvate α-enolase (ENO1) have all been found to be overexpressed or overactivated in cancer cells." (PMID 35434271, 2022). "In the membrane, ENO1 can promote the invasion and metastasis of carcinoma through activating fibrinolytic enzyme." (PMID 36295613, 2022). "In this review, we provide a comprehensive overview of the characterization, function, related transduction cascades of ENO1 and its roles in the pathophysiology of cancers, which is a consequence of ENO1 signaling dysregulation." (PMID 34671213, 2021). "In the cancer metabolic reprogramming, ENO1 stimulates cancer cells to create energy largely by disintegration of glucose in a non-oxidative manner rather than typical oxidative phosphorylation 17,18." (PMID 34671213, 2021).
cancer (continued). "The transcription, translation, post-translational modifying activities and the immunoregulatory role of ENO1 at the cancer development is receiving increasing attention." (PMID 34671213, 2021). "ENOblock 1, non-glycolytic inhibitor of ENO1, induce nuclear translocation of ENO1 and down-regulation of phosphoenolpyruvate carboxy kinase to inhibit the growth and migration of cancer cells 7,93,94." (PMID 34671213, 2021). "Previous studies showed that ENO1 was up-regulated and functioned as an oncogene in various cancer types." (PMID 34772911, 2021). "ENO1 was abnormally highly expressed in a wide range of cancers, and its high expression was connected with the clinicopathological characteristics of patients with tumors." (PMID 34504528, 2021). "And the growth of glycolysis and inhibition of invasion is the result of ENO1 downregulation in the cancer." (PMID 34671213, 2021). "In agreement with numerous studies on different human cancer types 13-19, 24-30, the study found that ENO1 protein was up-regulated in EC tissues in comparison with adjacent non-tumorous tissues." (PMID 33628097, 2021). "The identification of oncogenic ENO1 has triggered the development of small molecule inhibitors and others agents targeting ENO1 for cancer treatment." (PMID 34671213, 2021). "The studies of ENO1-related immune respond in the cancer is a promised thought for cancer immune therapeutics." (PMID 34671213, 2021). "And the most modifications of ENO1 are related with the substrate binding capacity, catalyst activity, cellular glycolysis and cell invasion and migration in cancer." (PMID 34671213, 2021). "A pool of recent findings has confirmed a strong relationship between ENO1 overexpression and cancer development." (PMID 34440098, 2021). "In conclusion, our study identified the specific expression of ENO1 on the invadopodial surface of a novel subset of highly invasive and pro-metastatic CSCs across different types of cancer." (PMID 34136381, 2021). "Herein, we mainly review the characterization, function, transduction cascades and inhibitors of ENO1 for depicting a detail portrait of ENO1 in the cancer development." (PMID 34671213, 2021). "Upregulation of ENO1 was detected in cancers of the stomach, breast, lung, colorectal, brain, kidney, liver, pancreas, and eye, as well as in non-Hodgkin’s lymphoma." (PMID 33968941, 2021). "We also observed the selective inhibition of the MTT-based viability of MDA-MB-231 cancer cells by recombinant Hsp90ab1, Eno1, and Ubc proteins, compared to that of the three lines of human epithelial cells of breast origin (KTB6, KTB22, and KTB34)." (PMID 34830748, 2021). "As a well-documented glycolytic enzyme responsible for ATP generation, ENO1 is related to mediate energy metabolism and cancer development." (PMID 34627260, 2021). "Since the energy of cancer cells mainly rely on the glycolysis, so that ENO1 has been developed as an important target in cancer treatment." (PMID 34671213, 2021). "As the important pathophysiological biomarker in the cancers, targeting ENO1 or ENO1-mediated signaling pathways has been received the most attention." (PMID 34671213, 2021). "The dose-response curves and the half maximal inhibitory concentration (IC50) data showed that the enolase inhibitor sensitivity of the cancer cell lines correlated with their ENO1 status." (PMID 34172075, 2021). "Regarding the other HGC-27 cancer cell line, the Pkm, Pfkl, Ldha, and Eno1 mRNA expression levels were significantly elevated in the NE treatment group." (PMID 33855088, 2021). "Previous studies have demonstrated that ENO1 played some significant role in protecting cells against adverse effects such as cancers, stresses, and other pathophysiological processes." (PMID 34349784, 2021). "Subsequent investigations demonstrated that these two cytokines cooperatively activated ERK1/2 signaling to promote ENO1-dependent glycolytic traits of cancer cells." (PMID 34312368, 2021).
cancer (continued). "The ENO1 are upregulation in the majority of clinically relevant cancers, and serum ENO1 auto-antibody have been reported in wide range of cancers." (PMID 34671213, 2021). "And, the expression of ENO1 in a variety of cancer types have been found to be dependent on the pathophysiological conditions." (PMID 34671213, 2021). "Cancer cells largely depended on glycolysis to generate energy, and ENO1 was one of the vital enzymes that promoted cell glycolysis." (PMID 34504528, 2021). "ENO1 is more important than other isoform in the glycolysis, and should be a potential target for cancer treatment." (PMID 34671213, 2021). "Recently, ENO1 has been proved to perform pivotal role in the tumorigenesis of numerous cancers and acts as a good prognostic indicator to monitor the disease progression." (PMID 33579362, 2021). "In the further, the ENO1 related immune in the cancer development should be further investigated to assess the immunotherapies of cancer." (PMID 34671213, 2021). "The expression regulation and dysfunction of ENO1 have a closely relationship with the hypoxic metabolic environment in the cancer development." (PMID 34671213, 2021). "Comparatively, blocking of LncRNA P5848/ENO1 axis can attenuate growth, survival and invasion capacity of cancer cells." (PMID 34671213, 2021). "Studies have shown that overexpression of ENO1 was correlated with poor prognosis in various types of cancer, including CRC 28, 32, 43-45." (PMID 32226539, 2020). "The study of ENO1 autoantibodies in CAR has uncovered a potential unintended consequence - i.e., antibody-induced retinal apoptosis- that requires careful consideration as ENO1-based cancer immunotherapies are developed." (PMID 33584813, 2020). "Below we summarize ENO1’s functions in cancer, growing potential as a cancer biomarker, and rising opportunities for targeting this enzyme for cancer treatment." (PMID 33584813, 2020). "These functions can be inhibited in cancer cells by ENO1 depletion, or targeting with antibodies, microRNA (miR), or long non-coding RNAs (lncRNAs)." (PMID 33584813, 2020). "In summary, this pan-cancer analysis demonstrated that increased ENO1 expression was correlated with poor prognosis and decreased immune infiltration levels in macrophages, CD4+ T cells, CD8+ T cells, and B cells in CESC and LUAD." (PMID 33643901, 2020). "ENO1 overexpression in a broad range of human cancers and targetability make it an attractive cancer biomarker candidate and therapeutic target." (PMID 33584813, 2020). "ENO1 has been reported to be a glycolytic enzyme which play vital roles in aerobic glycolysis and Warburg effect in cancer cells." (PMID 33176280, 2020). "These properties make ENO1 a tumor-associated antigen (TAA) and promising cancer biomarker and therapeutic target." (PMID 33584813, 2020). "Growing evidence suggests that ENO1 is upregulated in a broad range of human tumors, making it a candidate cancer biomarker." (PMID 33584813, 2020). "As a glycolysis enzyme, ENO1 can be overexpressed and activated by several glucose transporters and glycolytic enzymes that participate in the Warburg effect in cancer cells." (PMID 33067426, 2020). "The presence of peripheral ENO1-specific T cells is significantly correlated with improved survival, suggesting the prognostic value of these cells in cancers." (PMID 33643901, 2020). "These functions allow overexpressed ENO1 to promote cancer cell proliferation, survival, clonogenicity, epithelial-mesenchymal transition (EMT), chemoresistance, extracellular matrix degradation, migration, invasion, and metastasis." (PMID 33584813, 2020). "Another hub gene named ENO1 is also play an important role in tumorigenesis, cancer invasion, and metastasis." (PMID 32597160, 2020). "ENO1 is also localized on the surface of cancer cells where it enhances plasmin formation to promote extracellular matrix degradation, cell migration, invasion, and metastasis." (PMID 33584813, 2020).